GALE (UDP-galactose-4-epimerase)
Diseases named in the same sentence as GALE in open-access papers:
GALE is named in the same sentence as 36 diseases in open-access papers, as found by Europe PMC text mining. Sharing a sentence is not in itself a finding about the gene and the disease. The quoted sentences say what the papers report.
galactosemia (33 papers, 2009 to 2026). "UDP-galactose-4-epimerase (GALE) plays an essential role in galactose metabolism and has been implicated in both galactosemia and breast cancer through its effects on cellular metabolic processes." (PMID 41556698, 2026). "While GALE deficiency is known to cause galactosemia and thrombocytopenia, its impact on the human immune system remains largely unexplored." (PMID 41986803, 2026). "GALE deficiency (OMIM 230350) is caused by mutations in the GALE gene and presents with similar symptoms as those of classic galactosemia, including feeding problems, hypotonia, jaundice, and liver dysfunction." (PMID 38090149, 2023). "In mammals, GalE enzymes are necessary to generate the precursors for the sugar chains on intestinal mucins and mutations in human GalE are associated with galactosaemia." (PMID 37616327, 2023). "In some countries, NBS includes GALE deficiency as part of screening for galactosemia, either as a secondary target disorder, or as an additional finding." (PMID 36056436, 2022). "In these patients, GALE deficiency was suspected based on their clinical picture and after exclusion of classic galactosemia." (PMID 36056436, 2022). "The abnormal patterns found in GALE deficient patients are consistent with the serum transferrin glycosylation patterns in classic galactosemia." (PMID 36056436, 2022). "Deficits in three enzymes in this pathway, namely galactose-1-phosphate uridylyltransferase (GALT), galactokinase (GALK1), and UDP-galactose-4′-epimerase (GALE), are associated with genetic galactosemia." (PMID 34842598, 2021). "GALE deficiency (type III galactosemia) has two subtypes: the “general” type and the “peripheral” type." (PMID 34842598, 2021). "Note that kinetic alterations of genetic GALE variants are a continuum entailing a large scatter in the severity of galactosemia III26." (PMID 29921957, 2018). "Congenital defects in GALT result in galactosaemia-1 or classic galactosaemia, congenital deficit of galactokinase causes galactosaemia-2 whereas GALE deficiency leads to a rare form of galactosaemia." (PMID 27707936, 2016). "Partial loss of GALE in humans results in the spectrum disorder epimerase deficiency galactosemia; partial loss of GALE in Drosophila melanogaster also results in galactose-sensitivity, and complete loss in Drosophila is embryonic lethal." (PMID 22654673, 2012). "Deficiency of the UDP-galactose-4-epimerase (GALE) gene results in a form of galactosemia, with an inability to metabolise galactose and increases the risk of cataracts." (PMID 21092079, 2010). "Various missense mutations in GALK1, GALT, and GALE genes have been identified in patients with galactosemia." (PMID 19309526, 2009). "Moreover, mutations in the human GALT gene are associated with a pathological condition termed galactosemia, whereas mutations in the human GALE gene result in another disease called epimerase deficiency galactosemia." (PMID 40230451, 2025). "In humans, defects in the genes encoding galactokinase, GALT or GALE cause galactosaemia." (PMID 27707936, 2016). "Disparities such as this have raised the question of whether the pathophysiology of epimerase deficiency galactosemia results from the loss of GALE activity toward UDP-gal/UDP-glc, or toward UDP-galNAc/UDP-glcNAc, or both." (PMID 22654673, 2012). "Current research on GALE’s role in skin biology remains limited, primarily concentrated in congenital galactosemia studies." (PMID 41556698, 2026). "GALE encodes UDP-galactose-4-epimerase, and mutations in GALE result in epimerase-deficient galactosemia, also referred to as galactosemia type 3, a disease characterized by early onset cataracts, liver damage, deafness, and mental retardation." (PMID 35240026, 2022).
galactosemia (continued). "Similar consensus analyses, not yet experimentally verified, point to a similar scenario for human UDP-glucose 4-epimerase (GALE), a metabolic enzyme associated with LOF inherited galactosemia due to structural destabilization and altered protein dynamics." (PMID 30011855, 2018). "Galactosemia is a genetic disease in which galactose accumulates in the body due to a deficiency of enzymes galactokinase (GALK), UDP-galactose 4-epimerase (GALE), and galactose-1-phosphate uridylyltransferase (GALT) involved in the metabolic process that converts galactose into glucose." (PMID 36900622, 2023). "GALE encodes UDP-galactose-4-prime-epimerase, and its deficiency is known to cause galactosemia." (PMID 37344829, 2023). "Thus, several types of galactosemia can be distinguished: type I resulting from GALT deficiency, type II resulting from GALK deficiency, type III resulting from GALE deficiency, and type IV resulting from GALM deficiency, respectively." (PMID 36615667, 2022). "The first case of generalized GALE deficiency was reported in 1981, describing a newborn that presented on day five with a severe clinical picture similar to classic galactosemia and with a lack of GALE activity in red blood cells and fibroblasts." (PMID 36056436, 2022). "In this example, we focus on galactosemia, a rare genetic metabolic disorder that is caused by a deficiency of one of the three enzymes GALK, GALT, and GALE (cf. pathway #3), which together constitute the so-called Leloir pathway converting galactose to UDP-glucose." (PMID 29921957, 2018). "Galactosemia results in the deficiency of enzymes in the Leloir pathway including galactokinase (GALK1), galactose-1-phosphate uridylyltransferase (GALT), galactose mutarotase (GALM), or UDP-galactose 4′-epimerase (GALE), any of which can compromise the metabolism of galactose." (PMID 35118398, 2021). "Genetic analysis of the galactosemia genes, namely, GALT, GALE, and GALK1, led to the identification of four novel and four rare variants of uncertain significance." (PMID 38090149, 2023). "Pathologically elevated blood galactose levels may occur because of deficient functioning of enzymes involved in galactose metabolism (e.g., GALK (galactokinase), GALT (galactose-1-phosphate uridyl transferase), or UDP-Galactose-4 epimerase (GALE)), a rare condition known as galactosemia." (PMID 31718111, 2019). "Galactosemia is aninherited disease that occurs as a result ofinsufficient or no synthesis of some enzymes (GALT, GALK, and GALE)in galactose metabolism." (PMID 38405530, 2024).
epimerase deficiency galactosemia (7 papers, 2012 to 2025). "In 1 patient (ID 137) the molecular analysis was essential for a diagnosis of galactose epimerase deficiency, due to GALE gene variants." (PMID 39856690, 2025). "In humans, mutations in GALE result in epimerase-deficiency galactosemia, a disease characterized by liver damage, early-onset cataracts, deafness and cognitive disability." (PMID 33841170, 2021). "Second, given the impact of GALE-loss on both male and female fecundity in flies, these results suggest that long-term studies of both male and female reproductive issues in epimerase-deficiency galactosemia patients might be warranted." (PMID 22654673, 2012).
Thrombocytopenia (4 papers, 2022 to 2026). A reduction in the number of circulating thrombocytes. "The first evidence of UDP-galactose-4-epimerase deficiency associated with hematological alterations was reported in 1995, in a four-year-old girl presenting with bruising, thrombocytopenia, and dysplastic cells in the bone marrow." (PMID 36982178, 2023). "Furthermore, GALE deficiency has recently been associated with thrombocytopenia." (PMID 36615667, 2022). "The phenotype of the patients with genetic alterations in GNE, SLC35A1, GALE and B4GALT is consistent with syndromic manifestations, severe inherited thrombocytopenia, and hemorrhagic complications." (PMID 36982178, 2023). "Notably, thrombocytopenia has also been described in various other types of CDG, including ALG1-, ALG8-, GALE-, GNE-, MPI-, PMM2-, and B4GALT1-CDG." (PMID 40613041, 2025).
cognitive delay (2 papers, 2021 to 2022). "The cause of the developmental delay was unknown, and it was stated that the influence of GALE deficiency could not be ruled out." (PMID 36056436, 2022).
cyst (2 papers, 2014 to 2023). A sac-like closed membranous structure that may be empty or contain fluid or amorphous material. "Considering its bifunctionality, GalE is not only key to the synthesis of trophozoite glycans, but probably is essential for the generation of chitin for the emerging cyst wall from sugars cleaved from the host intestinal mucin." (PMID 37616327, 2023). "Unlike E. histolytica, G. intestinalis incorporates GalNAc for the biosynthesis of its cyst material, and both E. histolytica and G. intestinalis may use their GalE to interconvert the N-acetylamino sugars cleaved from the host mucin for use in their cyst wall." (PMID 37616327, 2023). "The importance of the ability of GalE to interconvert UDP-GalNAc and UDP-GlcNAc may be that the trophozoites can generate precursors for their own cyst wall from the sugar subunits cleaved from host mucins." (PMID 37616327, 2023). "As E. histolytica possesses a β-N-acetylhexosaminidase, which potentially releases GalNAc and GlcNAc from human intestinal mucins; via the action of GalE, these building blocks can be utilised to generate UDP-GlcNAc, the precursor for the chitin of the amoebic cyst wall." (PMID 37616327, 2023).
gastric adenocarcinoma (2 papers, 2018 to 2019). "This study demonstrated that the GALE expression is associated with gastric adenocarcinomas with well and moderately differentiated histological grades." (PMID 31827638, 2019). "This study is aimed at investigating the differential tissue expression of GALE and its possible association with clinical-pathological parameters and the outcome of gastric adenocarcinoma patients." (PMID 31827638, 2019). "In our study, GALE expression in well and moderately differentiated gastric adenocarcinomas can be related to a less aggressive cellular profile, corroborating the association with the intestinal type of Lauren classification." (PMID 31827638, 2019). "Associations with clinical and pathological parameters and outcome in relation to GALE mRNA expression from the validation cohort corroborated our data regarding GALE protein expression in gastric adenocarcinoma tissues." (PMID 31827638, 2019).
glioblastoma (2 papers, 2021 to 2023). The most malignant astrocytic tumor (WHO grade IV). "Let-7i-5p directly targeted UDP-galactose-4-epimerase and Inhibitor of Nuclear Factor Kappa-B Kinase Subunit Epsilon to reduce glioblastoma cell proliferation and migration." (PMID 33775245, 2021). "And GALE can be regulated by hsa-let-7i-5p to inhibit human glioblastoma growth." (PMID 36750807, 2023).
glioma (2 papers, 2021 to 2024). A benign or malignant brain and spinal cord tumor that arises from glial cells (astrocytes, oligodendrocytes, ependymal cells). "GALE plays an important role in promoting the development of human glioma." (PMID 33553434, 2021).
thyroid tumor (2 papers, 2018 to 2022). A benign or malignant neoplasm affecting the thyroid gland. "In malignant thyroid nodules, a different expression of GALE has been reported, while SLC4A4 has been included in a 15-gene profile proposed as diagnostic biomarkers of thyroid tumour." (PMID 29304754, 2018).
African sleeping sickness (1 paper, 2013). "In fact, novel GalE inhibitors are being actively derived and tested against Trypanosoma brucei, the causative agent for African sleeping sickness." (PMID 23936064, 2013).
atopic dermatitis (1 paper, 2026). "To validate our computational findings regarding GALE as a potential therapeutic target, we performed a quantitative PCR analysis using an atopic dermatitis cell model." (PMID 41556698, 2026). "This study provides mechanistic insights into how the Eubacterium eligens group influences atopic dermatitis through vitamin precursor-mediated systemic immune modulation and identifies GALE as a novel therapeutic target." (PMID 41556698, 2026). "GALE expression levels were measured across three experimental conditions: control group (K), atopic dermatitis model group (M), and methotrexate-treated group (Y)." (PMID 41556698, 2026). "Quantitative PCR analysis revealed that while GALE expression showed only modest changes in the atopic dermatitis model (1.16-fold increase compared to controls), methotrexate treatment dramatically upregulated GALE expression by 4.04-fold." (PMID 41556698, 2026). "The interconnected roles of these proteins, particularly GALE’s metabolic functions, highlight important mechanistic links between gut microbiota dysregulation and atopic dermatitis pathogenesis." (PMID 41556698, 2026). "Our findings establish a causal relationship between specific gut bacteria (Eubacterium eligens group) and atopic dermatitis risk while identifying seven key bridging genes (AKR1C2, GALE, GGH, NR4A1, PLA2G4B, TYMS) that connect gut microbial metabolites to skin pathology." (PMID 41556698, 2026). "From a drug development perspective, GALE as an enzyme target provides clear structural foundations and mechanisms for designing novel small-molecule drugs, particularly addressing the precision treatment needs for skin barrier dysfunction in atopic dermatitis patients." (PMID 41556698, 2026). "The results revealed that GALE expression in the atopic dermatitis model group showed only a modest increase compared to controls (fold change = 1.16, representing a 16% increase), suggesting that GALE dysregulation may not be a primary driver in AD pathogenesis." (PMID 41556698, 2026). "GALE-based drug design strategies may include enzyme activity modulators, allosteric regulators, or metabolic pathway redirectors, potentially developing next-generation atopic dermatitis therapeutics with reduced side effects and enhanced targeting specificity." (PMID 41556698, 2026). "The high-affinity binding between methotrexate and GALE substantially exceeds its binding strength with the classical target TYMS, providing a novel theoretical framework for explaining methotrexate’s unique efficacy in atopic dermatitis treatment." (PMID 41556698, 2026).
B cell deficiency (1 paper, 2026). A broad classification of disorders where circulating numbers of B lymphocytes are decreased or ineffective. "CONCLUSION: The p.R51W GALE variant results in a distinct hematopoietic stress phenotype characterized by significant quantitative B-cell deficiency." (PMID 41986803, 2026).
renal failure (1 paper, 2017). "Deficiency in GALE leads to the human disorder known as galactosemia III which is associated with impaired growth, cognitive deficiencies, and liver and renal failure." (PMID 28654657, 2017). "Deficiency in GALE leads to the human disorder known as galactosemia III which is associated with impaired growth, cognitive deficiencies, and even liver and renal failure." (PMID 28654657, 2017).
retinal dystrophies (1 paper, 2021). "However, GALE deficiency has never been associated with retinal dystrophies (RD)." (PMID 34448047, 2021).
infection (5 papers, 2012 to 2022). The state of being infected such as from the introduction of a foreign agent such as serum, vaccine, antigenic substance or organism. "Infection of NLRP3- or NLRC4-deficient bone marrow-derived macrophages (BMDMs) with Salmonella revealed that inhibition of Caspase-1 by GalE was dependent on the NLRP3 inflammasome." (PMID 35630356, 2022). "To further investigate the mechanisms responsible for Caspase-1 activation by S. Enteritidis GalE protein, we monitored the activation of Caspase-1 in Nlrp3−/− and Nlrc4−/−-deficient BMDMs in response to infection with different mutant strains of S. Enteritidis." (PMID 35630356, 2022). "Notably, in P1-resistant Salmonella enterica, the efficiency of P1 infection can be drastically increased by mutations in either galU or galE." (PMID 33597173, 2021). "This approach can unmask gene(s) that become required in the absence of lic2A during infection, potentially accounting for the difference in the survival profiles between the galE and lic2A mutants we observed previously." (PMID 31157175, 2019).
tumor (5 papers, 2016 to 2025). "While all proteins, as expected, were correlated with tumor stage according to proteomic data, GANAB, THIC/ACAT2, SEPT8, PPIA, and GALE showed an inverse correlation with tumor size, whereas MYDGF displayed a positive correlation." (PMID 41441336, 2025). "E39 (GALE 301) is an HLA-A2 restricted, FBP-derived (191-199, EIWTHSYKV ) peptide, which was shown to enhance tumor-associated lymphocyte proliferation and anti-tumor function in pre-clinical trials." (PMID 27852036, 2017). "Nonetheless, the dysregulation of the amount of both GANAB and GALE suggests that alterations in their expression may lead to aberrant glycosylation, thereby contributing to tumor progression in NMIBC." (PMID 41441336, 2025). "This analysis led to the identification of genes generally associated with cancer cells (MUC1, LGALS3, UGDH, TSTA3, and GALE) or the stromal compartment (LGALS1, PSAP, LGALS9, IDS, and MGAT1) in most of the tumor types analyzed." (PMID 38384845, 2024). "Furthermore, the abundance of proteins such as GANAB, GALE, THIC, SEPT8, and MYDGF/C19orf10 correlated with tumor size, suggesting their potential as prognostic biomarkers." (PMID 41441336, 2025). "Interestingly, proteins inversely correlated with tumor size included GANAB and GALE." (PMID 41441336, 2025).
GALE also shares sentences with these, for which no sentence is quoted: cataract (3 papers); thyroid cancer (3); breast carcinoma (2); anemia (1); cancer (1); deafness (1); gastric cancer (1); genetic disease (1); lung carcinoma (1); metabolic disorder (1); Obesity (1); papillary thyroid carcinoma (1); primary immunodeficiency (1); rectum adenocarcinoma (1); renal carcinoma (1); Sepsis (1); thyroid nodule (1); trypanosomiasis (1); uterine corpus endometrial carcinoma (1); Werner syndrome (1).